CD4 (CD4 molecule)
Diseases named in the same sentence as CD4 in open-access papers (continued):
Sharing a sentence is not in itself a finding about the gene and the disease.
Sepsis (continued). "Therefore, we demonstrate that miR-223 affects the level of autophagy in CD4+ T lymphocytes via the regulation of FOXO1, thereby affecting the development of sepsis." (PMID 39439897, 2024). "The decrease in T lymphocyte subpopulations, Th CD4+ and Tc CD8+, was evident from day 1 of the confirmation of either sepsis or septic shock, prompting the inclusion of apoptosis as a key factor in the evolution of sepsis and septic shock." (PMID 39064603, 2024). "ROS measurement of lung tissue showed that EVs from patients with sepsis-induced lung injury and from LPS-treated CD4+ T cells further elevated ROS levels in CLP mice compared with EVs from control subjects and from untreated CD4+ T cells." (PMID 36959535, 2023). "However, Arg1 expression by CD4+ and CD8+ T cells has been described in patients with sepsis, indicating a potential role for generic infectious stimuli and/or an antigen-driven process mediated via the TCR." (PMID 37440306, 2023). "Presumably, Tα1 and/or VitC reduce the expression of CD4 + CD25 + T cells and reduce the proliferation of Treg cells that inhibit T cells, thereby mitigating the early stage of sepsis-induced rapid inflammation due to an excessive inflammatory response and the associated damage to the body." (PMID 36816800, 2023). "This suggests that after sepsis recovery, CD3+ T cells present a decrease of CD4 and CD8, which could be involved in an impairment of CD3+ T cell activation after sepsis." (PMID 38094297, 2023). "The higher the levels of CD4+ and CD4+/CD8+, the better the recovery of patients after treatment, showing a positive correlation, suggesting that there is an abnormal immune regulation in patients with sepsis." (PMID 36694784, 2023). "The results revealed that B cell naïve, Monocytes, Macrophages M0, and Eosinophils were more abundant in sepsis cluster 1 (P<0.05), while B cell memory, T cells CD8, T cells CD4 memory resting, and Macrophages M2 were more abundant in sepsis cluster 2 (P<0.05)." (PMID 38332910, 2023). "Researchers have found unique transcriptome patterns of multiple circulating immune cell subtypes, including B- and CD4+, CD8+, activated CD4+, and activated CD8+T lymphocytes, as well as NK, NKT, and plasma cell like dendritic cells in patients with advanced sepsis." (PMID 37330481, 2023). "The percentage of CD4+ T cells can predict the outcome of patients with sepsis It was confirmed in our study that the levels of CD3+, CD4+ and CD4+/CD8+ in patients with sepsis were significantly lower than those in the health control group, with a significant difference (p<0.05)." (PMID 36694784, 2023). "Thus, eCIRP released during sepsis induced APANs to aggravate ALI and worsen the survival of septic animals via CD4+ T cell activation, Th1 polarization, and IFN-γ–mediated hyper-NETosis." (PMID 37463445, 2023). "Four variables (Alb, cd4_abs [pretransplant CD4 count], elevated CRP and sepsis) were selected." (PMID 37155023, 2023). "Compared with normal cohort, patients with sepsis have higher monocytes, M0 macrophages, M2 macrophages, activated mast cells, neutrophils infiltration and lower CD8+ T cell, memory activity CD4+ T cell, follicular helper T cells, gamma delta T cells, activated dendritic cell infiltration." (PMID 37456759, 2023). "In a bioinformatics analysis of key genes in sepsis-induced ARDS, compared with patients with sepsis alone, patients with septic-ARDS had higher levels of activated memory CD4+T lymphocytes and naive B lymphocytes, and lower levels of CD8+ T lymphocytes in their lung tissues." (PMID 38035100, 2023). "Encouraged by the findings of elevated distribution of CD4+ T-cell-expressed DGKK in serum EVs from patients with sepsis-induced lung injury, the downstream pathway of DGK was examined for the involvement in the toxic effects of LPS-treated CD4+ T-cell-derived EVs on cultured A549 cells." (PMID 36959535, 2023).
Sepsis (continued). "Recently, several studies indicated that CD4 and STAT4 could be participated in the development of sepsis." (PMID 37620751, 2023). "CD4+ T cells were positively correlated with 28-day survival, and their abundance had the highest correlation with the TCR signaling pathway (R =0.83, P <0.01), which is down-regulated in patients with sepsis." (PMID 37077915, 2023). "Patients with or without sepsis, and patients with different severity of sepsis showed distinct immunophenotypes, as demonstrated by lymphocyte count and CD4+ T-cell expression of metabolic, functional and apoptotic receptors." (PMID 35898496, 2022). "The levels of IL-6, TNF-α, IL-1β, CD4+, and CD8+ in the three groups of patients were compared to analyze the correlation of blood glucose levels with inflammatory response and immune indicators in patients with sepsis." (PMID 35664433, 2022). "In light of this, we chose to initially determine how VISTA impacted sepsis-induced Treg polarization by comparing the CD4+Foxp3+ Treg populations in WT as opposed to VISTA-/- mice via flow cytometry." (PMID 35401514, 2022). "CD4+ T cells lose appropriate functions, and CD8+ T cells decrease cytotoxic functions post-sepsis." (PMID 36250055, 2022). "Moreover, the integrated profile of the lower CD3+CD4+CD69+T/CD3+CD8+CD69+T ratio, PCT>0.53 ng/ml, and CO2CP<26.5 mmol/l was favored to the differentiation of G- sepsis from G+ sepsis, with an AUC of 0.947 in the regression model." (PMID 36703970, 2022). "Sepsis-induced T lymphocyte alterations were characterized by a decreased cytokine production (mainly of IFN-γ and/or TNF-α, mostly for CD4+ T cells) and a decreased proliferation capacity (for both CD4+ and CD8+ T cells)." (PMID 36045686, 2022). "Ex vivo cultured T cells with MDSCs in the Th0 condition (without the presence of any T-cell stimulant) showed increased expression of CD4+FOXP3+ (p = 0.044) in sepsis patients, but no such increased expression was observed in HCs and w/o sepsis patients." (PMID 35720398, 2022). "Increasing studies have paid attention to the alteration of T lymphocyte subsets in bacteria-infected diseases, particularly in sepsis, and reported that the absolute counts of T lymphocytes (including CD3+ T cell, CD4+ T cell, and CD8+ T cell) significantly decreased in severe sepsis patients." (PMID 36443747, 2022). "Here, we report that Nrp‐1 and TGF‐β1 stimulate the stability of CD4+CD25+ Tregs in the presence of LPS and that Nrp‐1 contributes to the activity of recombinant TGF‐β1 by the regulation of TGF‐β1/Smads cell signaling in sepsis." (PMID 34758202, 2022). "CD4+, CD8+, and total T lymphocyte downregulations were reported within sepsis cases." (PMID 36199798, 2022). "Interestingly, in an experimental abdominal murine sepsis model, neutrophil IL-10 production was induced by IFN-γ from CD4+ T cells, thereby dampening local inflammation." (PMID 35732880, 2022). "Myocardial stress/injury after early sepsis is limited in females, with less cardiac infiltration of CD4 + leukocytes but independent of shedding of TNFα from peripheral circulating leukocytes." (PMID 35723764, 2022). "Low circulating CD4 T cells (p = 0.0007), CD8 T cells (p = 0.0008), naïve T cells (p = 0.008) and recent thymic emigrants (p = 0.01) were the key features in patients that developed sepsis." (PMID 36471343, 2022). "While controversially, some reports demonstrated that adoptive transfer of CD4+CD25+ Treg could promote bacterial clearance and improve survival rate in polymicrobial sepsis mice." (PMID 35252164, 2022). "HMBPP-activated γδT cells from healthy individuals adhered to E. coliefficiently and promoted the efficient proliferation of CD4+ aß T cells, whereas γδT cells from patients with sepsis did not do so." (PMID 35020851, 2022).
Sepsis (continued). "To verify this hypothesis, we used T cell-specific knockout mTOR and TSC1 mice to create sepsis models using the classical CLP method to observe the effects of mTOR on ERS and the apoptosis of mice CD4+ T cells and the potential molecular regulatory mechanism." (PMID 35759162, 2022). "Conversely, there is an increased proportion of Th17 CD4+ lymphocytes, and Th17 count is higher in sepsis survivors than in non-survivors." (PMID 36279072, 2022). "In the present study, we illustrated a novel discrimination model of the low ratio of CD3+CD4+CD69+T/CD3+ CD8+CD69+T, PCT>0.53 ng/ml, and CO2CP<26.5 mmol/L, which could strongly predict the diagnosis of the G- sepsis (versus G+ sepsis), with an AUC of 0.947." (PMID 36703970, 2022). "In contrast, γδ T cells from patients with sepsis were not able to induce the proliferation of CD4+ αβ T cells, indicating that their proliferation-inducing ability was, indeed, severely weakened." (PMID 35020851, 2022). "In critically ill patients without sepsis, if over 80% of the CD4+ T cells expressed BTLA, they developed nosocomial infections more easily and had longer hospital stays." (PMID 34163466, 2021). "Since multiple cell types, including lineage- ILCs, CD4+ T helper 17 (Th17) cells, CD8+ (Tc17) cells, and γδ T cells can produce and secret IL-17A, we then assessed the relative contribution of these cells to the elevated lung IL-17A in sepsis." (PMID 33995408, 2021). "Besides, it also restores the balance of CD4+/CD8+ and Th1/Th2 ratio and reduces the concentrations of IL-6, TNF-α, and HMGB1, thus inhibiting the systemic inflammatory response induced by sepsis to alleviate lung injury." (PMID 34057015, 2021). "CST7 was expressed lowly in in CD4+ T cells and monocytes and its expression in these cells did not change during sepsis (Data not shown)." (PMID 33868254, 2021). "Furthermore, the T-cell receptor signaling pathway was reported to release some activated T cells and nuclear factors, CD4+, CD8+, and NFATC2, to take the immune response in sepsis." (PMID 34938184, 2021). "We identified unique transcriptomic patterns for multiple circulating immune cell subtypes, including B- and CD4+, CD8+, activated CD4+ and activated CD8+ T-lymphocytes, as well as natural killer (NK), NKT, and plasmacytoid dendritic cells in late sepsis patients." (PMID 34484194, 2021). "T-cell activation of both CD4+ and CD8+ T cells, as well as T-cell cytokine production, was suppressed acutely and persistently after burn injury, while sepsis could account for 47% of post burn mortality." (PMID 34938184, 2021). "We next examined whether expression of CST7 is modulated in other leukocyte populations during sepsis using one cohort from the previous analysis that also included purified CD8+ T cells, NK cells, CD4+ T cell and monocytes as well as neutrophils." (PMID 33868254, 2021). "The sub analysis of healthy versus CCI CD4+ T-lymphocytes revealed unique differential expression of five genes not seen in the analysis of all late sepsis patients (upregulated: HBB, ETS1; downregulated: SMDT1, RPL41, MTRNR2L12)." (PMID 34484194, 2021). "In contrast, the expression of GzmA in the main T cell subsets (NKT, CD8+ T or CD4+ T cells) was very low and did not increase during sepsis." (PMID 33664861, 2021). "Not surprisingly, late sepsis CD4+ T-lymphocytes did not have differential expression of any HLA genes." (PMID 34484194, 2021). "Improved lymphocyte counts (CD4+ and CD8+ immune effector cells) in sepsis patients." (PMID 33920518, 2021). "Since the number and function of CD4+T and CD8+T cells decrease in elderly patients with sepsis, while Tregs increase in frequency and suppressive function in both aging and septic patients, IL-7 administration could a possible treatment strategy." (PMID 33532141, 2021).
Sepsis (continued). "In the analysis of healthy controls (n=5) to late sepsis CCI patients (n=3), scRNA-seq revealed differential expression of 16 genes in CD4+, 30 genes in CD8+, 26 genes in activated CD4+, 52 genes in activated CD8+, and 37 genes in regulatory T (Tregs) lymphocytes." (PMID 34484194, 2021). "It was reported that sepsis induces a decrease in CD4+ populations; therefore, it is important that any sepsis treatment not promote the depletion of this population, which is crucial to disease resolution." (PMID 34502521, 2021). "IL‐38 could enhance the immune response of CD4+CD25+Tregs, thereby amplifying Th2 polarization of effector T cells in sepsis." (PMID 31880383, 2020). "CLP-induced sepsis increased expression of Ox40 on splenic CD4 T cells which persisted up to 5 days, with no change on CD8 T cells." (PMID 33613563, 2020). "The CD4/CD8 T lymphocyte ratio was also significantly reduced in the sepsis group without treatment." (PMID 32076015, 2020). "We described sepsis-induced increase in IL-10 production by monocytes and CD4+ T cells but not B cells and CD8+ T lymphocytes." (PMID 33613540, 2020). "Acupuncture at ST36 might play a protective effect on maintaining immune balance in sepsis animals by upregulating CA3+, CD4+, and CD8+ lymphocytes expression and restoring an approximately average level of CD4+/CD8+ ratio." (PMID 32215037, 2020). "To further delineate the contributions of the sepsis influence directly on CD4 T cells or their environment, we utilized an adoptive transfer system wherein naive MOG-specific, TCR-transgenic 2D2 CD4 T cells were transferred into congenically distinct recipient mice." (PMID 33191915, 2020). "Depleting CD4+ cells with an antibody (Gk1.5) prior to sepsis induction had no influence on IgM secretion, but led to reduced serum IgG concentrations 14 days after CASP." (PMID 32425951, 2020). "Compared with uninfected control mice, CD4+ T cell count significantly decreased in all three MSS groups which represented C. albicans-infected mice and continued to decrease with aggravation of sepsis." (PMID 32431684, 2020). "However, it has been shown in an animal model of sepsis that, although naïve CD8+ T cells undergo HP, naïve CD4+ T cells fail to undergo HP." (PMID 32825352, 2020). "Overall numbers of both CD4+ and CD8+ T cells were reduced in infection and sepsis patients." (PMID 31658288, 2019). "Exogenous IL-1β was effective in CD4 T-cell expansion in a dose-dependent manner, implying that this cytokine, released from MLN DCs during sepsis, may play a role, at least partly, in promoting septic inflammation." (PMID 31323786, 2019). "Another study from 2016 on trauma patients found elevated Th17/CD4+ Treg ratios in trauma patients who developed sepsis, furthermore the ratio of Th17 cells to CD4+ Tregs was skewed in favor of Th17 cells in non-surviving patients." (PMID 31681282, 2019). "However, in the sepsis group, the percentage of CD3+CD4+ naive cells decreased over time (p = 0.025)." (PMID 31658288, 2019). "The frequencies of T cells expressing CD4 were significantly lower in patients with infection without sepsis, with concomitant increases in CD8+ T cells." (PMID 31658288, 2019). "The frequencies of CD4+ and CD8+ T cells that produced IFN-γ or IL-17 in response to any mode of stimulation were similar using PBMC from healthy donors and patients with infection only or sepsis." (PMID 31658288, 2019). "We analyzed the recovery of naive and effector/memory CD4+ and CD8+ T cell subsets and analyzed thymic output and T-cell receptor (TCR)-repertoire diversity 1 week, 1 month and 3.5 months after sepsis induction, representing the post-acute, late and very late time points, respectively." (PMID 30730978, 2019). "A clinical trial on sepsis patients demonstrated elevated Th17 cell percentages as well as increased Th17/CD4+ Treg ratios in non-survivors with a positive correlation to the acute physiology and chronic health evaluation II (APACHE II) score." (PMID 31681282, 2019).
Sepsis (continued). "Comparison of PD-1, PD-L1 and PD-L2 expression by B and CD4+ T cells between sepsis survivors and non-survivors." (PMID 29661225, 2018). "These three immuno-adjuvants were selected, as their primary cellular sites of action are CD4 and CD8 T cells, and are either currently clinically approved or actively in use in ongoing clinical trials for immunotherapy of sepsis or oncology [12–19 and NCT02797431, NCT02960854, NCT02274155]." (PMID 29944697, 2018). "Of note, our results indicate that expression of the CD43 isoform 1B11 significantly increases on both CD4+ and CD8+ T cells following sepsis, suggesting that this upregulation may play a role in sepsis-induced T cell apoptosis." (PMID 30226896, 2018). "Finally, we assess the role of regulatory T cells (TReg cells), defined as Foxp3+ CD25+ CD4+ cells, in the increased mortality observed in CD43-/- animals during sepsis." (PMID 30226896, 2018). "The CD4+, CD25+, CD127lo subset is one of several studied in sepsis." (PMID 30459764, 2018). "However, sepsis-induced immune cell apoptosis, resulting in an overwhelming depletion of immune cells, including T cells (CD4+ and CD8+), B cells, and DCs, is evident in prospective studies of adults with sepsis." (PMID 30555806, 2018). "However, relatively stable CD4/CD8 ratios and unaltered CD4+ proportions in peripheral blood during sepsis have been described in several studies." (PMID 30332984, 2018). "TReg cells can be found in both CD4+ and CD8+ T cell populations; therefore, we first determined whether the CD4+ and/or CD8+ T cell populations were impacted by early sepsis." (PMID 30069485, 2018). "Following sepsis induction, the frequency of S7+ CD4+ T cells did not change significantly over the course of 96 hr." (PMID 30226896, 2018). "In contrast, no increase in total CD4+ T cells was observed 1 week post sepsis induction in IL-7-treated septic mice, indicating a preferential expansion of Foxp3+CD25+ Tregs upon IL-7 treatment." (PMID 29466409, 2018). "Given the increase in frequency of cells expressing the CD43 isoform 1B11 in both CD4+ and CD8+ T cell populations following CLP we hypothesized that CD43 might be playing a pathophysiologic role during sepsis." (PMID 30226896, 2018). "Data is conflicting though as models of sepsis have demonstrated that antibody mediated depletion of Treg does not improve mortality and adoptive transfer of CD4+ CD25+ Treg early in the course of sepsis actually improves bacterial clearance and mortality." (PMID 30459764, 2018). "We next sought to determine the functionality of CD4+ T cell populations in cancer vs. non-cancer hosts during sepsis." (PMID 29338031, 2018). "Furthermore, the activation and expansion of CD4+CD25+ T cells contributes to the development of immunosuppression and sepsis after severe burns." (PMID 29980222, 2018). "Furthermore, EA at ST36 also improves intestinal mucosal immune barrier in sepsis by increasing the concentration of secretory IgA, the percentage of CD3+, γ/δ, and CD4+ T cells, and the ratio of CD4+/CD8+ T cells." (PMID 28810910, 2017). "Since the population of CD4+ pDCs in the bone marrow was not reduced in splenectomized mice during sepsis, we can exclude the migration of pDCs from the spleen into the bone marrow." (PMID 29218051, 2017). "Given the finding that CXCR4 is upregulated on CD4+ and CD8+ T cells during sepsis, we hypothesized that blocking these signals using a CXCR4 blocking agent could improve survival and immune dysregulation in a murine model of polymicrobial sepsis." (PMID 29232699, 2017). "Subsequent analysis showed that prior splenectomy did not prevent the sepsis-induced accumulation of CD4+ DCs in the bone marrow." (PMID 29218051, 2017). "Unlike CD4+ T lymphocytes sepsis induces a slight increase (which was not statistically significant) in CD8+ T lymphocytes apoptosis under our experimental conditions." (PMID 28932195, 2017).